CD4 (CD4 molecule)
Diseases named in the same sentence as CD4 in open-access papers (continued):
Sharing a sentence is not in itself a finding about the gene and the disease.
gastric cancer (continued). "CCL5, CCL22, CCL21, CCL2, and CCL15 were correlated with effector memory CD4 T cell in T1/T2 stage gastric cancer, and the number of cells was associated with the expression of IL3, IL17F, IL18, IL22, and IL31." (PMID 33426088, 2020). "For example, lncRNA H19, which is abnormally expressed in gastric cancer, influences the infiltration of cancer-associated fibroblasts (CAFs), macrophages, CD4+T cells, and CD8+T cells in the TME through the miR-378a-5p/SERPINH1 axis, thereby promoting the progression of gastric cancer." (PMID 41229433, 2025). "In addition to baseline level, circulating OX40+ CD4+ T cell/CD4+ T cell ≥ 15% was associated with better PFS in patients with advanced gastric cancer after treatment with nivolumab." (PMID 38576625, 2024). "“CD45 on CD4+” was identified to be causally related to both stomach cancer and colon cancer." (PMID 38533503, 2024). "To explore the association between the predictive capacity of the CD3+/CD4+ cell–myosteatosis in gastric cancer patients and the pTNM stage, we categorized 124 patients into an early pTNM stage (0/Tis + I + II) group and 66 patients into an advanced pTNM stage (III + IV) group." (PMID 38894548, 2024). "In our study, CD4 memory activated T cells were linked to survival of gastric cancer patients." (PMID 37696973, 2023). "Furthermore, the QUANTISEQ algorithm determined an increased abundance of B cells, M2 macrophages, and CD4 T cells in high-risk gastric cancer." (PMID 37711621, 2023). "Additionally, the EPIC algorithm identified higher levels of B cells, cancer-associated fibroblasts, CD4 T cells, endothelial cells, and macrophages in high-risk gastric cancer." (PMID 37711621, 2023). "The NLR is associated with the density of CD4+ T cells in gastric cancer." (PMID 37306187, 2023). "Univariate and multivariate Cox regression analyses demonstrated that lower CD8+ T and CD8+ Tm expressing PD-1 as well as PD-1+CD8+T/PD-1+CD4+T cell ratio were independent risk factors in advanced gastric cancer patients receiving immunotherapy plus chemotherapy." (PMID 37974194, 2023). "Dendritic cells resting, Macrophages M0, Macrophages M1, Macrophages M2, Mast cells activated, Mast cells resting, Monocytes, NK cells resting, T cells CD4 memory activated, T cells follicular helper were associated with the RiskScore in gastric cancer patients." (PMID 36003776, 2022). "Moreover, the following study showed that a high abundance of CD4+ memory T cells was associated with better survival in gastric cancer." (PMID 35721151, 2022). "In addition, systemic inflammation markers included NLR and prognostic nutritional index are associated with the density of CD4+T cells in the tumor microenvironment of 288 gastric cancer patients." (PMID 34141607, 2021). "Here, our study uncovers a novel mechanism of CAF-mediated immune evasion in gastric cancer: FAP+CAFs facilitate the transition of naive CD4+ T cells toward a Th2 phenotype through IL-31 secretion." (PMID 40843362, 2025). "In gastric cancer, mesenchymal stem cells stimulated by activated CD4+ T cells, have been shown to enhance the migration and growth potential of gastric cancer cells in BALB/c nu/nu xenografts." (PMID 40182754, 2025). "Prognostic models incorporating immune features—such as a ceRNA network involving MASTL, or populations including CD4+ memory T cells, monocytes, and neutrophils—show utility in predicting clinical outcomes in gastric cancer." (PMID 41208974, 2025). "To provide functional evidence for this finding, we further validated the interaction between FMR1 in gastric cancer cells and CD4+ T cells through in vitro assays." (PMID 41184982, 2025). "This cascade facilitates the differentiation of naive CD4+ T cells into Th2 cells, thereby contributing to resistance against anti-PD-1 therapy in gastric cancer." (PMID 40843362, 2025). "Studies have shown that in studies related to gastric cancer, high expression of PD-1 is found in CD4+ and CD8+T cells." (PMID 39713872, 2025).
gastric cancer (continued). "Our study showed that the CD4 + T cell was an independent predictor of both immunotherapy efficacy and prognosis in advanced gastric cancer, suggesting the indispensable tumor suppressive capacity of CD4 + T cells in immunotherapy." (PMID 38491354, 2024). "In gastric cancer, T cell CD4 memory activated is involved in its prognosis through metabolic reprogramming, which directly leads to apoptosis and correlates with ferroptosis by releasing substances such as perforin and granzyme." (PMID 39720726, 2024). "Morphine suppresses the immune function of gastric cancer patients by regulating the percentage of CD4+, CD25+, FoxP3+ regulatory T lymphocytes (Tregs) in vitro and increasing the CD4+/CD8+ ratio and Tregs." (PMID 39295870, 2024). "In patients with advanced gastric cancer, a high proportion of CD4 + T cells, NK cells, and Treg cells were independent predictors of PFS with immunotherapy." (PMID 38491354, 2024). "This is consistent with human gastric lymph nodes showing increased RORγT in CD4+ T cells in the early stages of gastric cancer." (PMID 38014984, 2024). "Research has shown that in the gastric cancer TME, inhibiting the expression of ferroptosis-related genes (FRGs) in CD4+ Th cells weaken their activation, which is associated with poor tumor prognosis." (PMID 39726588, 2024). "An imbalance in CD4+ T cell subsets, particularly a shift from Th1 to Th2 dominance, is often observed in the gastric cancer microenvironment." (PMID 39906672, 2024). "CALD1 expression correlates positively with immune cells such as CD8+ T cells, CD4+ T cells, macrophages, neutrophils, and others in gastric cancer." (PMID 38717641, 2024). "In another study, human gastric cancer patient tumour MDSCs suppressed T cells ex vivo via IL-10, resulting in a decrease in CD4+ T cell production of IL-2 and IFNγ consistent with impaired effector function." (PMID 38464388, 2024). "According to these results, LDN slowed the decrease in CD3 + T cells and CD4+ T cells after gastric cancer treatment." (PMID 38720250, 2024). "In summary, our study preliminarily presented relatively high value of peripheral memory PD-1+CD8 + T and PD-1+CD8+T/PD-1+CD4+T ratio in predicting response and prognosis to immunotherapy plus chemotherapy in patients with advanced gastric cancer." (PMID 37974194, 2023). "A prognostic model of CD4+T cells is urgently needed to improve treatment strategies and explore the specifics of this interaction between CD4+T cells and gastric cancer cells." (PMID 37274740, 2023). "Our study found that MEblue is a key module of gastric cancer, which contains gene groups related to the level of activated CD4 memory T Cell infiltration." (PMID 37274740, 2023). "Correlation analysis between DCE-MRI parameters and CD4+ TILs in patients with advanced gastric cancer." (PMID 37342362, 2023). "Without a doubt, more exploration is necessary to determine the mechanism of CD4 T cells-mediated survival in gastric cancer." (PMID 37696973, 2023). "The circulating memory PD-1+CD8+ T cells and PD-1+CD8+T/PD-1+CD4+T cell ratio revealed high predictive values for response and prolonged survival outcomes in advanced gastric cancer patients receiving immunotherapy." (PMID 37974194, 2023). "Then, we evaluate the proportion of multiple immune-related cells in gastric cancer cohort, especially for CD4 and CD8 cells." (PMID 38035067, 2023). "It has been confirmed that the number of CD4+ T cells increased in gastric cancer tissue and peripheral blood of patients with gastric cancer, while the number of CD8+ T cells decreased." (PMID 36765353, 2023). "In our quest to decode the immune dynamics within gastric cancer, we turned to IHC to assess the expression patterns of critical immune markers, specifically CD4, CD8, and CD20, which are pivotal in delineating T cell and B cell populations." (PMID 38035067, 2023).
gastric cancer (continued). "In gastric cancer patients, CD4+ T cells and regulatory T cells were enriched, and lower expression of miR-128-3p was correlated with overall survival." (PMID 37696973, 2023). "Herein, we have investigated the predictive values of circulating CD8+ T cells and CD8+T/CD4+T cell ratio in advanced gastric cancer patients receiving immunotherapy." (PMID 37974194, 2023). "Increasing CD4+ memory cell density in gastric cancer has been reported to be a predictor of prolonged patient survival, while further studies have shown that CD4+ T cells are more infiltrated in gastrointestinal tumors compared to normal tissue." (PMID 36386179, 2022). "We found that high tumor SFRP4 expression (P=0.024), family history of gastric cancer (P=0.005), high CD4 expression (P=0.009), and high CD8+T expression (P=0.048) were risk or protective factors for OS in patients in univariate analysis." (PMID 35847366, 2022). "CD8+FoxP3+ Tregs have a suppressive role in different types of cancers such as prostate, colorectal, hepatic and gastric cancers, similar to CD4+FoxP3+ T cells." (PMID 35804964, 2022). "Other recent study has found that the number of CD4+ T cell fractions is increased in gastric cancer, while the CD8+ T cell fraction is decreased." (PMID 36003776, 2022). "• Increased miR-128-3p expression decreases CD4+ regulatory T cells enrichment.• IL16 promotes CD4+ regulatory T cells enrichment.• miR-128-3p affects the proportion of CD4+ regulatory T cells by targeting IL16 in gastric cancer." (PMID 34968167, 2022). "(2020) generated a gastric cancer cell line tumor model in mice, performed scRNAseq analysis, and found that successful tumor growth required Il17a in tumor-infiltrating CD4+ Ths." (PMID 35757757, 2022). "Of note, the upregulation of CD4+ TILs is accompanied by FOXP3+ Treg infiltrations in HER2-amplified gastric cancer." (PMID 36591290, 2022). "Patients with gastric cancer and a low CD4 to CD8 ratio also exhibited 3.6-times higher overall survival compared with patients with a high ratio." (PMID 36430209, 2022). "In our experiments, CD8+ and activated memory CD4+ T cells were negatively correlated with NRG risk score, indicating a critical role of necroptosis in the anti-tumor immune response of gastric cancer." (PMID 36092932, 2022). "Meanwhile, a significant negative correlation was found between FNDC5 and the abundance of CD4+ memory T cells in gastric cancer." (PMID 36386179, 2022). "A study has proved that the more CD4+ memory T cells infiltrated in gastric cancer, the longer the patients' survival time." (PMID 36684237, 2022). "In contrast, another study revealed that patients diagnosed with the diffuse type of gastric cancer had a higher density of T cells (CD4+ and CD8+) than that of patients with the intestinal type." (PMID 36010915, 2022). "In the immune microenvironment of gastric cancer, more naïve B cells, memory resting CD4+ T cells, Treg cells, monocytes cells, and resting mast cells were infiltrated in the high-risk group." (PMID 35058980, 2022). "Many studies have shown that the expression of TILs (CD3, CD4, CD8) is associated with a favorable prognosis in gastric cancer." (PMID 35719985, 2022). "By using the TIMER database, we analysed the correlation between the expression of CD44 and 6 kinds of infiltrating immune cells, namely, B cells, CD8+ T cells, CD4+ T cells, macrophages, neutrophils and dendritic cells, in gastric cancer." (PMID 36316684, 2022). "Autoreactive inflammation against parietal cells is induced by CD4+ T cells in TxA23 mice, resulting in atrophic gastritis and metaplasia, ultimately leading to gastric cancer." (PMID 35735608, 2022). "Effector CD45RA-FoxP3+CD4+ Tregs subset infiltrating the tumors has also been reported to express VEGFR-2 in advanced gastric cancer patients." (PMID 33854498, 2021).
gastric cancer (continued). "The evaluation of immune infiltrates in gastric cancer showed that ARHGAP11A expression was significantly associated CD8+ T cells, CD4+ T cells, macrophages and dendritic cells." (PMID 34733886, 2021). "We have previously reported that the neutrophil-to-lymphocyte ratio (NLR) and prognostic nutritional index (PNI) were associated with the density of CD4+ immune cells in TIME, which leads to prognostic values of systemic inflammation in gastric cancer." (PMID 34086741, 2021). "In gastric cancer patients, higher levels of infiltration in their CD4+ T cells, macrophages, neutrophils, and dendritic cells were positive associated with the expression of Notch receptors." (PMID 32028262, 2020). "In conclusion, three immune molecular clusters and a ten CD4+ MTRG signature were established for gastric cancer patients." (PMID 33816214, 2020). "More specifically, treated tumors presented lower expression of PD1+ in both the CD4+ and CD8+ T cell subsets, which has been associated with better five-year overall survival rates in patients with gastric cancer." (PMID 32708639, 2020). "PCOLCE was correlated with immune infiltrating levels including those of B cells, CD8 + T cells, CD4 + T cells, macrophages, neutrophils, and DCs in gastric cancer patients." (PMID 33392251, 2020). "For T cell subpopulations, the fractions of activated memory CD4+ T cells and Tregs increased in gastric cancer compared with normal tissue (P<0.01), while the resting memory CD4+ T cell fraction decreased in gastric cancer tissue (P<0.05)." (PMID 32969836, 2020). "The fractions of plasma cells and resting memory CD4+ T cells decreased, while those of activated memory CD4+ T cells and Tregs increased in gastric cancer." (PMID 32969836, 2020). "Among gastric cancer, in the early and middle stages (T1/T2 stage, T1/2), the most infiltrating immune cells were effector memory CD4 T cells and immature B cells, which is the same in advanced gastric cancer (T3/T4 stage, T3/4)." (PMID 33426088, 2020). "From inflammation to gastric cancer, most immunoinflammatory cells showed a downward trend such as central memory CD4 T cell." (PMID 33426088, 2020). "Foxp3+ and CD4+ T cell counts were also increased in gastric cancer in CVID patients (p = 0.001; p = 0.003), in this case in keeping with the results obtained in the whole series (Section 3.3)." (PMID 32575504, 2020). "In contrast, increased numbers of CD4 + T cells in peripheral blood mononuclear cells were significantly related to poor prognosis in gastric cancer with short telomere length." (PMID 32512904, 2020). "Patients with well‐differentiated gastric cancer had higher levels of tumor‐infiltrating CD4 + T cells (P = .009);." (PMID 31631566, 2019). "In summary, increased LAYN expression correlates with poor prognosis and increased immune infiltration levels in CD8+ T cells, CD4+ T cells, macrophages, neutrophils and DCs of multiple cancers, especially in colon and gastric cancers." (PMID 30761122, 2019). "Gastric cancer patients with smaller tumor size (<5 cm) exhibited higher levels of CD4 + T cells (P = .003) and CD8 + T cells (P = .002)." (PMID 31631566, 2019). "In our study, gastric cancer patients with smaller tumors (<5 cm) had higher CD4 + T and CD8 + T cell levels." (PMID 31631566, 2019). "Higher CXCR3 expression is correlated with increased CD8+ and CD4+ cell infiltration, and low CXCR3 expression is associated with poor prognosis in gastric cancer." (PMID 31696204, 2019). "Well‐differentiated gastric carcinomas displayed higher peripheral (P = .029) and tumor‐infiltrating CD4 + T cell (P = .009) populations and a higher tumor‐infiltrating DC1/DC2 ratio (P = .048)." (PMID 31631566, 2019). "Patients with well‐differentiated gastric carcinoma displayed higher levels of CD4 + T cells (P = .029)." (PMID 31631566, 2019). "There are some researches focusing on the relationship between the subsets of CD4+ T cell and the progress and prognosis of gastric cancer." (PMID 29682534, 2018).
gastric cancer (continued). "This shows that JPBS combined with chemotherapy can significantly improve the expression level of CD4+/CD8+ for the treatment of gastric cancer." (PMID 29675052, 2018). "And there are many subsets of T cells which play different roles in gastric cancer, CD4+ T cell, including regulatory T cells, CD8+ T cell, and CD45RO+ memory T cells." (PMID 29682534, 2018). "For example, peripheral blood CD19+CD24hiCD38hi Bregs isolated from gastric cancer patients converted CD4+CD25− effector T cells into CD4+FOXP3+ Tregs via expression of TGF-β." (PMID 28261223, 2017). "In patients with gastric cancer, elevated peripheral blood levels of certain CD4+ T cell subpopulations, including Th22 (CD4+IL-22+IL-17−IFN-γ−) and Th17 cells were found to be associated with increased tumor progression." (PMID 28805741, 2017). "Bregs were shown to play an immunosuppressive role in gastric cancer by inhibiting Th cytokine production, but also by converting CD4+CD25– effector T cells to CD4+Foxp3+ Tregs in a TGF-β1-dependent way." (PMID 28470464, 2017). "In another study on patients with gastric cancer and esophageal cancer, a correlation between percentage of Tregs (CD4+ CD25high with Foxp3 mRNA) with the severity of disease was observed in both cancers." (PMID 27866241, 2017). "In gastric cancer tissue, the percentage of Tregs among the CD4+ T cell subset was substantially increased compared to that of Tregs among peripheral blood CD4+ T cells from the controls." (PMID 26799288, 2016). "We have demonstrated that high levels of Tregs among tumor-infiltrating CD4+ T cells were favorable, but an increased proportion of MDSCs was an adverse independent prognostic factor in gastric cancer." (PMID 26799288, 2016). "A past study revealed that PD-1 expression on CD4+ and CD8+ T cells from gastric cancer tissue was significantly higher than that on CD4+ and CD8+ T cells from PBLs." (PMID 26901565, 2016). "As expected, we found a positive correlation between CD24hiCD38hiBregs and CD4+FoxP3+Tregs in gastric cancer." (PMID 26378021, 2015). "Increased tumor progression in patients with gastric cancer has been tied to increased peripheral blood levels of certain CD4+ T-cell subpopulations, including Th22 (CD4+IL-22+IL-17−IFN-γ−) and Th17 (CD4+IL-17+IFN-γ−) cells." (PMID 26695753, 2015). "Increased CD19+CD24hiCD38hiBregs positively correlate with levels of CD4+FoxP3+Tregs in gastric cancer." (PMID 26378021, 2015). "GMF isolated from human gastric cancer and H. pylori infected tissues co-cultured with CD4+ T cells induced substantially higher levels of Th17 than GMF from normal tissues in an IL-6, TGF-β, and IL-21 dependent manner." (PMID 23365642, 2013). "The ratio of activated CD4 T cells/Tregs <1 suggests poor prognoses in gastric cancer patients." (PMID 40901678, 2025). "In the gastric cancer cohort, it was indicated that expression of Schlafen family genes, among others, SLFN11, was positively associated with infiltration of numerous immune cells, including CD4+ T cells and CD8+ T cells." (PMID 40649874, 2025). "This study also demonstrated that FMR1 expression was positively correlated with activated CD4+ memory T cells and M1 macrophages, but negatively correlated with Tregs and monocytes, providing new insights into tumor immunotherapy for gastric cancer patients with high FMR1 expression." (PMID 41184982, 2025). "In gastric cancer, CD4 T cells are upregulated and fibroblasts and plasma cells are downregulated." (PMID 39120585, 2024). "PLXDC2 expression is related to T cell CD4 memory resting proportion within gastric cancer." (PMID 38564630, 2024). "Treg cells are part of CD4 + T cells (approximately 5%) and patients with gastric cancer show increased numbers of regulatory T cells in the peripheral blood and tumor-infiltrating lymphocytes, however, the role of Treg cells in tumor progression remains controversial." (PMID 38491354, 2024).